ACTN1 (actinin alpha 1)
Diseases named in the same sentence as ACTN1 in open-access papers (continued):
Sharing a sentence is not in itself a finding about the gene and the disease.
cancer (32 papers, 2009 to 2025). A tumor composed of atypical neoplastic, often pleomorphic cells that invade other tissues. "We finally aimed to study the genes implicated in cancer cell migration as a mechanism of rescue, thus we analyzed the expression of ACTN1, PTGS2, and RAC1." (PMID 40032892, 2025). "Previous studies have indicated that the loss of ACTN1 inhibits cancer cell proliferation, invasion, and migration, while ACTN1 itself can promote tumor growth and metastasis." (PMID 39968416, 2025). "Dysregulated ACTN1 function has been implicated in the pathogenesis of a diverse range of diseases, such as cancer, rheumatoid arthritis, congenital macrothrombocytopenia, and nemaline myopathy." (PMID 38057867, 2023). "The ACTN1 gene is also a protein-coding gene and associated with cancer." (PMID 38435719, 2024). "ACTN1 is highly expressed in various tumors and has a known impact on the prognosis of cancer patients." (PMID 38307919, 2024). "ACTN1 has been reported to show up-regulation within BC, which participates in cancer progression by inducing partial EMT." (PMID 34546849, 2021). "On the other hand, ACTN1 expression was significantly associated with global survival, especially in HPV− cancers." (PMID 34830760, 2021). "ACTN1 silencing disrupted cancer cell adhesion to murine surgical wounds and thereby prolonged the tumor-free survival." (PMID 31413748, 2019). "We propose that ACTN1 may influence the physical interactions between cancer cells and their extracellular matrix, which could modulate integrin β1 activation." (PMID 38057867, 2023). "Furthermore, IHC analysis indicated a marked decrease in the staining intensities of Ki-67 and CD44, markers of cellular proliferation and cancer stemness, respectively, under conditions of ACTN1 depletion." (PMID 38057867, 2023). "Notably, the potential to generate secondary PDXs was significantly reduced in tumor cells treated with a combination of ACTN1 inhibition and cisplatin, compared to the robust tumorigenicity exhibited by cancer cells receiving other individual treatments." (PMID 38057867, 2023). "Only a few studies are available on the role of ACTN1 in cancers." (PMID 34546849, 2021). "Overexpression of ACTN1 in the high-invasiveness score group was detected in 15 cancer types and suggested potential resistance to eight drugs, including Oxaliplatin and Leflunomide, both of the which target DNA replication (r = 0.401 and r = 0.349, respectively)." (PMID 33766047, 2021). "Similarly, a comparative analysis was conducted between open GEO database (GSE118916, GSE79973, GSE26942, GSE56807, and GSE54129) in GC samples and non-carcinoma adjacent samples, revealing that ACTN1 was overexpressed in GC (P < 0.05)." (PMID 34546849, 2021). "Furthermore, ACTN1 was upregulated in 408 GC samples relative to 211 non-carcinoma adjacent samples according to the public databases TCGA and GTEx as per the GEPIA (P < 0.05)." (PMID 34546849, 2021). "Among them are genes involved in cell adhesion/migration processes (PEPD), migratory potential of cancer cells (ACTN1), ECM (LTBP2, PRG4, ADGRL1, CD9), or in metabolic processes (LDHD, ALDH7A1), as well as proto-oncogenes or their ligands/inhibitors (FYN, PPP1R13L)." (PMID 30838002, 2019). "Therefore, targeting ACTN1-mediated YAP activation may serve as a potential approach to cancer therapy." (PMID 38307919, 2024). "Subsequently, the protein level of ACTN1 was assessed by WB, which showed that 8 of the 10 pairs had increased levels of ACTN1 within GC samples relative to adjacent samples; this finding was further verified by RT-qPCR of 19 GC samples and matched non-carcinoma samples (P = 0.0042)." (PMID 34546849, 2021). "However, the reason why ACTN4, rather than ACTN1, is frequently associated with cancer malignancies despite similarities in domain structure, actin-binding and-crosslinking activities, and Ca2+-sensitivity between the two remains to be elucidated." (PMID 25860875, 2015).
cancer (continued). "Previous study showed that ACTN1 is central to PDAC micropinocytosis, extracellular matrix processing, and chemotherapeutic uptake facilitating cancer survival." (PMID 41007761, 2025). "Overexpression of ACTN1 in certain cancer cells induces EMT, and inhibition of Actn1 by Oroxylin A decreases expression of αSMA and suppresses EMT." (PMID 36149903, 2022). "Out of 52 genes investigated, we observed that many genes upregulated in M2 and downregulated in M1 macrophages–ACTN1, FLRT2, MRC1, PTGS1, RHOJ, TMEM158–correlated positively with the EMT scores (first 6 rows) across multiple cancer types." (PMID 30729096, 2019). "With respect to the cancer group, the upregulation of mir-195-3p, KLK11, A1AG2, SMIM1, and the downregulation of mir-3176, mir-205-5p, novel-hsa-mir-208-3p, mir-3529-3p and let-7i-3p, CXCL7, TBB1, ACTN1 and BIP were identified compared with the non-cancer group." (PMID 39787026, 2024). "The overexpressed proteins, including actinin α1 isoform (ACTN1), annexin A5 (ANXA5), cathepsin D (CTSD), F-actin-capping protein subunit β (CAPZB), inorganic pyrophosphatase (PPA1), and tubulin α1c chain (TUBA1C), are related to cellular structure, growth, or cancer cell invasion." (PMID 38249992, 2024). "We found that ACTN1 and ITGA5 could interact with other genes to regulate some diseases and this study first explored the interaction between ACTN1 and ITGA5 in the regulation of cancer progression." (PMID 36742137, 2023).
tumor (30 papers, 2006 to 2025). "ACTN1, upregulated in OC and linked to poor prognosis, promotes tumor growth, EMT, and M2 macrophage polarization via ERK1/2 signaling; FBXO25 interacts upstream, and ERK1/2 inhibition partially reverses these effects." (PMID 41280929, 2025). "Collectively, these findings above suggest that ACTN1 is profoundly implicated in the tumor growth of HCC cells." (PMID 33413564, 2021). "Using this replication population of samples, they were able to detect seven genes with tumour-specific splice variants (ACTN1, CALD1, COL6A3, LRRFIP2, PIK4CB, TPM1 and VCL)." (PMID 24179441, 2013). "Furthermore, heightened expression of ACTN1 is intricately linked to tumor cell motility, metastasis, and invasiveness." (PMID 38836761, 2024). "In addition, ACTN1 deficiency repressed the growth and metastasis of tumor tissues in tumor xenografts of nude mice." (PMID 36742137, 2023). "After collecting evidence using different approaches, we found that ACTN1 was overexpressed in tumor tissues and associated with significantly poor prognostic outcomes, which indicated that ACTN1 might act as an oncogene in GC." (PMID 34546849, 2021). "This may provide theoretical supports for a new method based on ACTN1 to prevent tumor migration caused iatrogenically by surgical manipulation." (PMID 34546849, 2021). "Interestingly, we found that the expression of ACTN1 was closely associated with alpha-fetoprotein level, tumor thrombus, tumor size and TNM stage." (PMID 33413564, 2021). "Expression levels of β-catenin and its downstream targets were significantly reduced, while GSK-3β levels were noticeably increased in PDX-derived tumor cells subjected to ACTN1 depletion." (PMID 38057867, 2023). "We have confirmed that the expression of ACTN1 in tumor tissues of HNSCC patients was increased, which had a relation with the low overall survival." (PMID 36742137, 2023). "Crucially, we revealed a synergistic effect between ACTN1 depletion and cisplatin treatment in diminishing tumor growth, both in a xenograft and a PDX model." (PMID 38057867, 2023). "What’s more, ACTN1 depletion also repressed the growth and metastasis of tumor tissues in tumor xenografts of nude mice." (PMID 36742137, 2023). "Western blot analysis confirmed a persistent increase of ACTN1 in tumor tissues relative to ANTs, suggesting a potential role for ACTN1 as a tumor promoter in HNSCC." (PMID 38057867, 2023). "Our in vivo experiments further provided support for these findings, as MYH9 depletion in SCC-1cisR cells notably decreased the tumor size, weight, and volume, which had all been increased by ACTN1 overexpression." (PMID 38057867, 2023). "These tumor-promoting effects of ACTN1 overexpression were largely counteracted by MYH9 downregulation." (PMID 38057867, 2023). "To assess intrahepatic HCC tumor growth, we orthotopically injected sh-ACTN1 and control MHCC-97H cells into nude mice." (PMID 33413564, 2021). "Histological H&E staining of the liver tissues showed that mice transplanted with sh-ACTN1–1 cells had lesser intrahepatic tumor nodules than those transplanted with sh-Ctrl cells." (PMID 33413564, 2021). "The in vitro and in vivo experiments revealed that ACTN1 is crucial for the cell proliferation and tumor growth of HCC." (PMID 33413564, 2021). "In conclusion, in this study we found that ACTN1 is crucial for the cell proliferation and tumor growth of HCC." (PMID 33413564, 2021). "As a result, we found that ACTN1 knockdown significantly retarded tumor growth as revealed by reduced tumor weight." (PMID 33413564, 2021). "In vivo subcutaneous xenograft model and intrahepatic transplantation model were generated to decipher the contribution of ACTN1 in the tumor growth of HCC." (PMID 33413564, 2021).
tumor (continued). "It was found that the expression of ACTN1 is closely related with tumor size, TNM stage, and patient prognoses." (PMID 33413564, 2021). "ACTN1 still remains a potential molecule to be explored for its contribution toward the tumor burden." (PMID 31269666, 2019). "An in vivo tumor regression result was correlated to the cell viability data obtained in 4T1 cells and showed a highly significant reduction in tumor volume upon delivery of ACTN1-CA complex compared to the CA control." (PMID 31269666, 2019). "Exons 19a and 19b of ACTN1 appear to be mutually exclusive exons, with 19a predominant in tumor samples and 19b predominant in normal samples." (PMID 17192196, 2006). "Together with our data, these observations support a critical role for ACTN1 in conferring chemoresistance in tumor cells, and its targeting holds potential to re-sensitize tumors to taxane-based chemotherapeutics agent, which are still standard care of treatment regimens for TNBC patients." (PMID 38480932, 2024). "ACTN1 imparts promotive impacts on tumor growth in hepatocellular carcinoma." (PMID 36742137, 2023). "Importantly, in vivo studies further confirmed that tumor growth driven by ACTN1 upregulation was halted by β-catenin depletion." (PMID 38057867, 2023). "We then evaluated whether MYH9 depletion could counteract the tumor-promoting role of ACTN1 in HNSCC." (PMID 38057867, 2023). "Notably, silencing MYH9 significantly attenuates ACTN1's tumor-promoting effects, supporting the notion that ACTN1 drives HNSCC tumorigenesis primarily by boosting MYH9-dependent GSK-3β degradation." (PMID 38057867, 2023). "Knockdown of ACTN1 suppressed in vitro cell proliferation and in vivo tumor growth of HCC cells." (PMID 33413564, 2021). "al., used small interfering RNAs to reduce the expression of ACTN1 in murine tumor cells." (PMID 31413748, 2019). "A subgroup of the tumour-specific splicing variations (ACTN1, CALD1, and VCL) was observed in all three organs and may indicate general cancer-related splicing events." (PMID 24179441, 2013). "Also, other genes (PTGS2, RAC1, and ACTN1) that are involved in tumor metastasis were found to be significantly upregulated in the CAM-DOX SH-SY5Y cells as compared to CTRL, which could be implicated in their mobilization and metastasis." (PMID 40032892, 2025). "Indeed, blocking the YAP-TEAD axis can significantly inhibit ACTN1-mediated tumor growth." (PMID 38307919, 2024). "Interference of ACTN1 could improve the survival rate of xenograft tumor rats." (PMID 36742137, 2023). "Therefore, it is logically rational to deduce that ACTN1 could play a role similar to that of ACTN4 in tumor development." (PMID 34546849, 2021). "In addition, ACTN1 expression was also high in HNSCC cells and downregulation of ACTN1 could also suppress cell proliferative, migrative and invasive abilities as well as EMT in HNSCC, and reduce the tumor growth in xenograft tumor mice, which was in line with the role of ACTN1 in other tumors." (PMID 36742137, 2023). "Second, the impact of ACTN1 targeting on the TME and tumor immunity in HNSCC necessitates further investigation." (PMID 38057867, 2023). "In line with the in vitro findings, ACTN1 depletion in SCC-1cisR and SCC-23cisR cells led to a significant reduction in tumor size, volume, and weight in vivo." (PMID 38057867, 2023). "Otherwise, actinin alpha 1 (ACTN1) expression, acyl-CoA dehydrogenase Long-chain (ACADL)/YAP, and YAP/Forkhead Box M1 (FOXM1) are proposed targets for preventing tumor growth and early recurrence of HCC." (PMID 36033517, 2022). "ACTN1 is highly expressed in HCC tissues and acts as a tumor promoter by suppressing Hippo signaling via physical interaction with MOB1." (PMID 33413564, 2021).
tumor (continued). "In this study, we found that ACTN1 was significantly upregulated in HCC tissues and closely related to tumor size, TNM stage or patient prognoses." (PMID 33413564, 2021). "It was found that ACTN1 was significantly upregulated in HCC tissues and closely related to llpha-fetoprotein level, tumor thrombus, tumor size, TNM stage and patient prognoses." (PMID 33413564, 2021). "Intravenous delivery of CTNNA1 siRNA with CA nanoparticles significantly reduced tumor volume in the initial phase of the study, while siRNAs targeting CTNNB1, TLN1, VCL, PXN, and ACTN1 genes significantly decreased the tumor burden at all time points." (PMID 31269666, 2019). "Cluster 1 comprises genes important for skeletal muscle (ACTA1) and muscle function (ACTN1) and includes a crucial gene (AKT1) known to regulate insulin signaling, cell survival, and tumor progression, as well as two chaperones: HSPA1A and HSPB1 (heat shock proteins (HSPs))." (PMID 36767649, 2023). "Intriguingly, the inhibition of AKT does not entirely eliminate the tumor-promoting effects and the upregulated β-catenin-mediated signaling resulting from ACTN1 overexpression, suggesting the possibility of additional underlying molecular mechanisms." (PMID 38057867, 2023). "Additionally, the intensities of Ki67 and CD44 staining, enhanced by ACTN1 upregulation, were markedly reduced by MYH9 downregulation in xenograft tumor tissues." (PMID 38057867, 2023). "Genetic silencing of ACTN1 suppresses HCC cell proliferation and tumor growth." (PMID 33413564, 2021). "When ACTN1 was knocked down, MOB1 could interact with LATS1, then increase the phosphorylation of LATS1/YAP and activate Hippo signaling, which led to the inhibitory effects on the tumor growth of HCC." (PMID 33413564, 2021).
bacterial infections (1 paper, 2022). "Upregulated ACTN1 level also stimulates the action of integrin β1, which are expressed specifically on leukocytes during inflammation and promote cellular adherence, phagocytosis, and cytotoxic effects, especially during bacterial infections." (PMID 35457192, 2022).
infection (1 paper, 2025). The state of being infected such as from the introduction of a foreign agent such as serum, vaccine, antigenic substance or organism. "Although many ACTN1 cytoskeletal interactions were preserved in infection, both RTN4 and TGOLN2 were lost." (PMID 41389964, 2025). "In both mock and infection conditions, the ACTN1 interactome was distinct to that observed in A375 cells." (PMID 41389964, 2025).
renal disorders (1 paper, 2015). "Missense mutations in ACTN1, ACTN2 and ACTN4 cause dominantly inherited platelet, cardiac and renal disorders respectively, while a nonsense mutation in ACTN3 seems to have been beneficial during the recent evolution of some human populations." (PMID 26312134, 2015).
ACTN1 also shares sentences with these, for which no sentence is quoted: acute lymphoblastic leukemia (2 papers); cervical carcinoma (2); COVID-19 (2); prostate carcinoma (2); active tuberculosis (1); acute myeloid leukemia (1); adenomyosis (1); Alzheimer disease (1); amoebiasis (1); Angelman syndrome (1); aortic stenosis (1); breast tumor (1); cardiomyopathy (1); cerebellar ataxia (1); chronic pancreatitis (1); cyst (1); depression (1); distal arthrogryposis (1); escherichia coli infection (1); esophageal squamous cell carcinoma (1); focal segmental glomerulosclerosis (1); heart diseases (1); hemophilia A (1); Hepatitis (1); human papillomavirus infection (1); Huntington disease (1); hyperlipidemia (1); hypertrophic cardiomyopathy (1); IgA nephropathy (1); liver diseases (1).
A further 20 diseases each share a sentence with ACTN1 in 1 paper.